KCNJ11 (potassium inwardly rectifying channel subfamily J member 11)
Diseases named in the same sentence as KCNJ11 in open-access papers (continued):
Sharing a sentence is not in itself a finding about the gene and the disease.
infection (6 papers, 2010 to 2022). The state of being infected such as from the introduction of a foreign agent such as serum, vaccine, antigenic substance or organism. "E. coli 83972fim and E. coli 83972 infection generated an increase in K+ channel protein levels, compared to uninfected control cells (TWIK, TRAAK and KCNJ11), with E. coli 83972fim showing the most pronounced effects." (PMID 31181116, 2019).
metabolic disorders (2 papers, 2016 to 2017). "The rs5219 SNP—which causes the K23E substitution in KCNJ11 gene —maps to the consensus of the nuclear receptor PPARγ, and it is predicted to alter the binding affinity of this TF, a crucial player in glucose and lipid homeostasis and that is associated with metabolic disorders." (PMID 27347941, 2016). "Pyrosequencing analyses were performed for the candidate genes KCNJ11, PPARγ, PDK4, KCNQ1, SCD1, PDX1, FTO and PEG3 in peripheral blood leukocytes (PBLs) from 25 patients diagnosed with only T2D, 9 patients diagnosed with T2D and MetS and 11 control subjects without any metabolic disorders." (PMID 28727822, 2017).
psychiatric disorder (1 paper, 2016). A disorder characterized by behavioral and/or psychological abnormalities, often accompanied by physical symptoms. "We aimed to characterize the types of psychiatric disorders present in children and adolescents with KCNJ11 mutations, and explore the impact of these on families." (PMID 27086753, 2016). "We aimed to characterize the types of psychiatric disorders present in children with KCNJ11 mutations, and explore their impact on families." (PMID 27086753, 2016). "Case reports and animal data suggest that KCNJ11 mutations may be associated with childhood psychiatric disorders." (PMID 27086753, 2016). "KCNJ11 is also expressed in the brain, and ~ 20% of those affected have neurological features, which may include features suggestive of psychiatric disorder." (PMID 27086753, 2016).
retinopathy (1 paper, 2024). "The frequency of retinopathy was low, and the presence of microalbuminuria was 0% in ABCC8‐MODY and KCNJ11‐MODY, while microalbuminuria ranged from 1.8% in HNF4A‐MODY and HNF1A‐MODY to 16.7% (1 out of 6 individuals) in KLF11‐MODY." (PMID 39511990, 2024).
KCNJ11 also shares sentences with these, for which no sentence is quoted: Hyperinsulinemia (8 papers); insulinoma (7); ischemia (6); type 1 diabetes (5); Cantu syndrome (3); gestational diabetes mellitus (3); heart disease (3); melanoma (3); myocardial infarction (3); Cardiac Arrhythmias (2); cardiac hypertrophy (2); cardiomyopathy (2); cervical cancer (2); dilated cardiomyopathy (2); genetic disease (2); Hypoinsulinemia (2); hypokalaemia (2); maturity-onset diabetes of the young (2); oligodendroglioma (2); ovarian cancer (2); permanent neonatal diabetes mellitus (2); Abdominal obesity (1); acanthosis nigricans (1); atherosclerosis (1); autism (1); autism spectrum disorder (1); Bartter syndrome (1); bladder cancers (1); Brugada syndrome (1); cardiac conduction defect (1).
A further 51 diseases each share a sentence with KCNJ11 in 1 paper.